OPTN (optineurin)
Diseases named in the same sentence as OPTN in open-access papers (continued):
Sharing a sentence is not in itself a finding about the gene and the disease.
glaucoma (continued). "In the first study of families affected with NTG where OPTN mutations were observed, it was reported that M98K polymorphism was associated with glaucoma." (PMID 29951055, 2018). "Regarding its disease associations, mutations in the optineurin gene are associated with glaucoma and have more recently been found to correlate with Paget’s disease of bone and amyotrophic lateral sclerosis (ALS)." (PMID 29867991, 2018). "In this review, we highlight the main functions of OPTN and how glaucoma-associated mutants alter these functions." (PMID 29951055, 2018). "Certain mutations in OPTN are associated with glaucoma, an eye disease that causes irreversible blindness, and amyotrophic lateral sclerosis (ALS), a motor neuron disease." (PMID 30083281, 2018). "Certain mutations in OPTN (gene OPTN) are associated with primary open angle glaucoma, a leading cause of irreversible blindness, and amyotrophic lateral sclerosis, a fatal motor neuron disease." (PMID 29951055, 2018). "Previously, we have observed that M98K polymorphism in OPTN, associated with glaucoma, shows enhanced Tbk1-mediated phosphorylation at Ser-177, which is required for increased LC3-II production and autophagosome formation in retinal cells." (PMID 30083281, 2018). "Several missense mutations of OPTN have been reported that are associated with glaucoma, such as E50K, H26D, H486R, E322K, etc.." (PMID 29951055, 2018). "A number of studies have suggested that mutations in optineurin that cause glaucoma are a result of defective autophagy." (PMID 29867991, 2018). "Considerable interest in OPTN came from the identification of mutations in the OPTN gene in patients with degenerative diseases such as glaucoma, ALS, and FTD." (PMID 29692786, 2018). "This RGC-like property of selective induction of cell death by glaucoma-associated mutants of OPTN provides further support to the suggestion that the 661W cells are RGC precursor-like cells." (PMID 29951055, 2018). "Another glaucoma-associated variant of OPTN, M98K, induces cell death and Tbk1-dependent phosphorylation selectively in RGC-5 cells but not in IMR32 or HeLa cells." (PMID 29203899, 2017). "Compared to WT OPTN, two glaucoma-associated mutants of OPTN, E50K and M98K, induced significantly more cell death in these cells." (PMID 29203899, 2017). "This suggests that the damaging effects of glaucoma-associated mutants of OPTN are cell type specific." (PMID 29203899, 2017). "Endocytosis abnormalities in glaucoma are associated with OPTN mutations, shown to interrupt transferrin receptor recycling and promote autophagic death." (PMID 28575017, 2017). "Mutations in OPTN were already known to cause primary open-angle glaucoma when it was found that both dominant and recessive mutations in OPTN cause ALS." (PMID 27164932, 2016). "This protein is regulated by optineurin, a pathogenic gene associated with primary open angle glaucoma (POAG)." (PMID 27429799, 2016). "Mutations in optineurin (OPTN) are linked to the pathology of primary open angle glaucoma (POAG) and amyotrophic lateral sclerosis." (PMID 27654856, 2016). "Apparently, more studies, especially quantitative proteomic analyses, are required to dissect the in vivo targets of OPTN E50K mutation in motor neurons, thereby to clarify how E50K mutation found in OPTN is associated with human glaucoma disease." (PMID 27620379, 2016). "Recently, studies of glaucoma have identified disease-causing genes (OPTN and TBK1) that directly interact with each other in the same biological pathway." (PMID 27275741, 2016). "Sequence variants in the gene for optineurin have been reported to be associated with normal tension glaucoma, a subtype of primary open-angle glaucoma." (PMID 25939269, 2015). "Quite a few mutations in OPTN are reported in glaucoma, though only a few mutations, including E50K and M98K have been shown to alter cellular homeostasis and cause degeneration of retinal cells by engagement of distinct mechanisms." (PMID 26376340, 2015).
glaucoma (continued). "A glaucoma-associated variant of OPTN, M98K, induces autophagic degradation of transferrin receptor (TFRC) and death in retinal cells." (PMID 26376340, 2015). "We also show that Tbk1, a glaucoma-associated protein, through its catalytic activity, induces death in retinal cells and this requires autophagic function of OPTN." (PMID 26376340, 2015). "In conclusion, our results show that a glaucoma-associated mutation, M98K, of optineurin enhances its phosphorylation at Ser177 by activating Tbk1 protein kinase." (PMID 26376340, 2015). "The mechanism by which the most typical glaucoma-associated mutation in OPTN, E50K, contributes to glaucoma has always been unclear." (PMID 24983867, 2014). "The increase in cell death seen with loss of OPTN is often discussed in relation to the neuronal cell death that is seen in patients with glaucoma or ALS." (PMID 25329564, 2014). "Recently, we have shown that a glaucoma-associated variant of optineurin, M98K, causes enhanced autophagy leading to TFR degradation and death of retinal cells." (PMID 24752605, 2014). "More, recently, Minegishi and coworkers reported that the over-expression of a glaucoma causing-mutation in OPTN, Glu50Lys, produces an accumulation of insoluble OPTN protein that can be blocked with chemical inhibition of TBK1 activity in HEK293 cells." (PMID 24883232, 2014). "We next examined the influence of glaucoma-associated OPTN mutations on OPTN oligomerization, as well as the type of bonds formed." (PMID 24983867, 2014). "Optineurin, one of the archetypal glaucoma-causing genes, is usually degraded via the proteasome pathway in RGCs." (PMID 23901248, 2013). "Genome-wide association studies showed that only two identified genes, myocilin (MYOC) and optineurin (OPTN), are well-established glaucoma-causing genes." (PMID 24019741, 2013). "Wild-type optineurin or its glaucoma-associated mutants (E50K, H486R and R545Q) were co-transformed with CYLD in yeast." (PMID 21408173, 2011). "Our results show that a glaucoma-associated mutant of optineurin, H486R, is altered in its interaction with CYLD." (PMID 21408173, 2011). "Optineurin was identified as a gene mutated in certain glaucomas, a group of neurodegenerative eye diseases that cause blindness, and recently in familial amyotrophic lateral sclerosis." (PMID 21408173, 2011). "Optineurin is a pathogenic gene associated with primary open angle glaucoma (POAG), in which the retinal ganglion cells (RGCs) are targeted." (PMID 22194658, 2011). "In the future, further in vitro and in vivo studies are required to show that optineurin causes glaucoma via regulating Bdnf, Ntf3, Snap25, and Nef1." (PMID 22194658, 2011). "OPTN has also been associated with various forms of glaucoma, including POAG and normal tension glaucoma." (PMID 21655191, 2011). "Though mutations in optineurin have been associated with glaucoma and more recently with amyotrophic lateral sclerosis, the functional defects caused by these mutations are not completely understood." (PMID 21408173, 2011). "Mutations in optineurin, encoded by the OPTN gene, are associated with certain glaucomas, a group of neurodegenerative eye diseases that cause blindness." (PMID 20085643, 2010). "Genetic evidence suggests that the E50K (Glu50Lys) is a dominant disease-causing mutation of optineurin which was found in 13.5% of families with hereditary glaucoma." (PMID 20085643, 2010). "Mutations in optineurin are associated with glaucoma, a neurodegenerative eye disease that causes blindness." (PMID 20085643, 2010). "Nevertheless, the nature of functional alterations caused by mutations in optineurin and their probable role in etiopathogensis of glaucoma are unclear." (PMID 20085643, 2010). "Except for specific mutations in the MYOC and OPTN genes, details regarding the predicted clinical course associated with a glaucoma gene mutation cannot be provided." (PMID 21217896, 2010).
glaucoma (continued). "Nonetheless, more than 25 studies dealing with the impact of OPTN coding and flanking intronic variants on glaucoma show that disease-causing sequence alterations are rare in POAG/NTG patients and families." (PMID 19754948, 2009). "Mutations in optineurin are associated with certain glaucomas, a group of eye diseases that cause blindness." (PMID 19340308, 2009). "A novel mutation of a Lys322Glu change in OPTN is responsible for this familial case of primary open-angle glaucoma observed in northeastern China." (PMID 19710941, 2009). "A glaucoma-associated mutant of optineurin, E50K, showed significantly more inhibition of TNFα-induced NF-κB activation in HeLa cells." (PMID 19340308, 2009). "Coding variants in the optineurin gene (OPTN, GLC1E) have been reported to play a role in primary open-angle glaucoma (POAG) in various populations." (PMID 19096531, 2008). "Additional studies in larger data sets will be necessary to corroborate the role of these OPTN variants in glaucoma." (PMID 19096531, 2008). "Previous reports have indicated that mutations of OPTN are responsible for moderate to mild forms of late onset glaucoma and are specific for normal tension glaucoma (NTG)." (PMID 18385781, 2008). "The genetic association between OPTN variants and glaucoma has been extensively studied in different populations." (PMID 19096531, 2008). "This study has contibuted additional evidence of association of OPTN E50K with glaucoma, and reported an additional instance of the 691_692insAG sequence variant." (PMID 17293779, 2007). "Mutation in the optineurin gene was initially reported in 16.7% of families with hereditary primary open angle glaucoma (POAG), with most of them having NTG." (PMID 17563722, 2007). "The original report of OPTN involvement in glaucoma presented three likely disease-causing variants designated E50K, 691_692insAG, and R545Q, and one proposed risk factor M98K." (PMID 17293779, 2007). "Our study contributes additional evidence to support the previously reported association of the OPTN E50K mutation with glaucoma." (PMID 17293779, 2007). "Genotype frequencies of optineurin single nucleotide polymorphisms in primary open-angle glaucoma, adult-onset ocular hypertension, and control subjects." (PMID 17615537, 2007). "Previously known and novel mutations detected in the CYP1B1, MYOC, and OPTN genes in primary open-angle glaucoma patients." (PMID 17563717, 2007). "Allele frequencies of optineurin single nucleotide polymorphisms in primary open-angle glaucoma, adult-onset ocular hypertension, and control subjects." (PMID 17615537, 2007). "OPTN is broadly expressed in critical organs such as the brain, retina, and heart, and pathogenic mutations in the gene have been linked to neurodegenerative conditions, including glaucoma and amyotrophic lateral sclerosis (ALS)." (PMID 41294799, 2025). "E50K mutation in OPTN is associated with severe forms of glaucoma and a worse prognosis." (PMID 39448868, 2025). "However, it was only the glaucoma-associated E50K and M98K mutations that increased stopped OPTN in both F0 and F1 analyses, and only the E50K mutation that increased both OPTN and LC3b in both F0 and F1 analyses." (PMID 40795095, 2025). "However, hereditary POAG associated with OPTN gene mutations is a glaucoma form affecting only a minority of POAG patients; therefore, the results obtained in the E50K model cannot be generalized to the overall cohort of POAG patients." (PMID 41227293, 2025). "Furthermore, we confirmed that a glaucoma causative mutation in optineurin, OPTN-E50K, sensitizes cells to RIP1-mediated inflammatory cell death." (PMID 39448868, 2025). "Since the mitophagy receptor Optineurin (OPTN) is one of few large-effect glaucoma genes and axonal damage occurs at the optic nerve head in glaucoma, here we explored whether OPTN mutations perturb the transcellular degradation of mitochondria." (PMID 40795095, 2025).
glaucoma (continued). "Conversely, the versatility of this system to model aspects of barrier dysfunction relevant to glaucoma was tested using an hPSC line with a glaucoma-specific Optineurin (E50K) mutation as well as a paired isogenic control, where MVECs then exhibited reduced barrier integrity." (PMID 39543684, 2024). "As previous studies have suggested barrier dysfunction as one of several phenotypes associated with the progression of glaucomatous neurodegeneration, we then decided to assess the possibility of changes to barrier integrity as a result of the glaucoma-associated OPTN(E50K) mutation." (PMID 39543684, 2024). "While the emphasis of this study was upon the effects of RGCs and astrocytes with the glaucoma-associated OPTN(E50K) mutation upon barrier-forming MVECs, in future studies it will be of interest to explore the impact of a dysfunctional barrier upon RGCs and astrocytes." (PMID 39543684, 2024). "In addition, the OPTN p.(Asn51Thr) variant was isolated from proband’s family members diagnosed with glaucoma." (PMID 39669598, 2024). "Interestingly, another glaucoma-associated variant of OPTN, M98K, also triggered autophagy-dependent retinal cell death." (PMID 37725658, 2024). "Indeed, ATG9 vesicles are incorporated into condensates containing a glaucoma-associated OPTN mutant and synapsin." (PMID 39420095, 2024). "Furthermore, studies have shown an association of OPTN with glaucoma in Japanese, Indian, Chinese, Korean and Finnish patient populations." (PMID 37566048, 2023). "Thus, further studies are required to determine the impact of optineurin mutations for mitophagy in human glaucoma as well as in other diseases." (PMID 37034386, 2023). "Future studies should investigate whether inhibition of ER stress prevents RGC degeneration induced by OPTN mutations in animal models of glaucoma." (PMID 35346303, 2022). "OPTN has also been genetically associated with neurodegeneration in glaucoma and ALS30–32, suggesting that our findings may contribute to novel therapies for neurodegenerative diseases." (PMID 33864025, 2021). "The glaucoma-associated E50K mutation in optineurin (OPTN) is known to affect autophagy and cause the apoptosis of retinal ganglion cells (RGCs), but the pathogenic mechanism remains unclear." (PMID 33723228, 2021). "The E50K mutation in the OPTN (Optineurin) gene is a leading cause of inherited glaucoma." (PMID 34638582, 2021). "It has also been demonstrated that OPTN E50K mutation-mediated glaucoma may be triggered via disruption of interaction between OPTN and Rab8 GTPase." (PMID 32545285, 2020). "In other words, ACZ treats glaucoma, which shares a causal mutation in the OPTN gene with ALS." (PMID 31797619, 2020). "In addition, mutations in optineurin (OPTN), an adaptor protein that is involved in autophagy, are associated with glaucoma patients, suggesting a role of autophagy in pathogenesis of glaucoma." (PMID 30692515, 2019). "Thus, it appears that E50K mutation alters several functions of OPTN, which contribute to cell death associated with glaucoma pathogenesis." (PMID 29951055, 2018). "In contrast, optineurin mutations have been frequently reported in glaucoma." (PMID 29875767, 2018). "Since then, OPTN has been identified as a ubiquitin-binding protein involved in many signaling pathways and cellular processes, and mutations in the OPTN gene have been associated with glaucoma, Paget’s disease of bone and neurodegenerative pathologies." (PMID 29692786, 2018). "Therefore, these cells can be used for exploring the molecular mechanisms of cell death and other functional defects caused by glaucoma-associated mutants of OPTN." (PMID 29951055, 2018). "Secretory defects have also been associated with optineurin in glaucoma." (PMID 29875767, 2018). "Glaucoma-associated mutations of OPTN are mostly missense mutations." (PMID 29951055, 2018).
glaucoma (continued). "Therefore, it is not surprising that a cell line, 661W, which expresses markers of both RGCs and cone photoreceptors, shows selective induction of cell death by two glaucoma-associated mutants of OPTN." (PMID 29203899, 2017). "In addition to using molecular marker analysis, we examined the effect of overexpression of two glaucoma-associated mutants, E50K and M98K, of OPTN in 661W cells." (PMID 29203899, 2017). "Consequently, defects in TBK1 or OPTN and autophagy are a plausible cause of the retinal ganglion cell death and optic nerve damage that are central features of glaucoma." (PMID 27275741, 2016). "M98K variant of OPTN is associated with glaucoma in certain ethnic groups." (PMID 26376340, 2015). "Notably, upregulation or mutation of optineurin, product of another glaucoma gene, also leads to inhibition of the proteasomal activity and induction of autophagy." (PMID 24732711, 2014). "A glaucoma-causing mutant of optineurin, E50K, induces death selectively in retinal cells." (PMID 24752605, 2014). "Although several glaucoma-associated mutants of optineurin have been tested to induce death of retinal cells, only E50K and M98K variants are able to induce more cell death than wild type optineurin." (PMID 24752605, 2014). "We tested the hypothesis that some of the glaucoma-associated mutants of optineurin may be altered in their interaction with CYLD." (PMID 21408173, 2011). "A glaucoma-associated mutant of optineurin (H486R) shows reduced binding to CYLD." (PMID 21408173, 2011). "The protein encoded by OPTN is involved in many biologic processes including some that lead to apoptosis, however, the mechanism by which mutations in this gene cause glaucoma is unknown." (PMID 21321670, 2011). "Since NF-κB and optineurin have been linked to glaucoma, their reciprocal regulation might have relevance to etiopathogenesis of glaucoma." (PMID 19340308, 2009). "Our study implicates that apart from OPTN mutations observed in monogenic inheritance of glaucoma also OPTN common allelic variants may influence an individual's susceptibility for developing NTG in a multigenic inheritance pattern." (PMID 19754948, 2009). "Finally, since the E50K OPTN mutation causes glaucoma, we then asked whether increased transcellular degradation might be associated with vision loss." (PMID 40795095, 2025). "Thus, some or all of the pathological activity of glaucoma-associated OPTN mutations may occur outside of the RGCs themselves." (PMID 40795095, 2025). "Therefore, variants in the OPTN gene may contribute to some additional risk of glaucoma in certain patient populations." (PMID 38241218, 2024). "However, a recent study indicated that mutations in OPTN may cause glaucoma via mechanisms other than defective mitophagy." (PMID 37725658, 2024). "This work suggests that OPTN gene mutation in glaucoma may be mitophagy independent." (PMID 33168089, 2020). "Eventually, the multifunctional protein was renamed to OPTN (“optic neuropathy inducing”), as it was found to play a major neuroprotective role and mutations in this gene were shown to be causative for the development of primary open-angle glaucoma, a leading cause of blindness." (PMID 29692785, 2018). "Optineurin protein may function to protect the optic nerve from tissue necrosis factor α–mediated apoptosis, and loss of function of this protein may decrease the threshold for ganglion cell apoptosis in patients with glaucoma." (PMID 21921986, 2011). "Based on our current and previous findings, we surmise that the defective trafficking, along with fragmentation of the Golgi complex and increased apoptosis, may be the underlying basis how the E50K optineurin mutation renders the patients predisposed to the glaucoma pathology." (PMID 20634958, 2010). "Three glaucoma-associated mutations, E50K, M98K, and H486R; an ALS-associated mutation, E478G; two synthetic OPTN mutations, F178A and D474N, disrupting LC3b and ubiquitin binding, respectively." (PMID 40795095, 2025).